LPAR6 (lysophosphatidic acid receptor 6)
Diseases named in the same sentence as LPAR6 in open-access papers (continued):
Sharing a sentence is not in itself a finding about the gene and the disease.
lung carcinoma (3 papers, 2020 to 2023). "Two cohorts (GSE3141 and GSE4573) of lung cancer demonstrated that high expression level of LPAR6 was associated with better prognosis (OS HR = 0.53, 95% CI = 0.36 to 0.80, Cox p = 0.00206181; OS HR = 0.53, 95% CI = 0.31 to 0.91, Cox p = 0.0219869)." (PMID 34769557, 2021). "So, it is conceivable that high LPAR6 expression is an independent risk factor and leads to a better prognosis in lung cancer patients, and a hazard ratio (HR) below 0 indicates LPAR6 expression is a protective factor." (PMID 34769557, 2021). "We analyzed the protein level of LPAR6 in two independent lung cancer patient cohorts with 74 and 77 paired lung cancer and normal tissues, respectively." (PMID 34769557, 2021). "LPAR6 is mainly expressed in the cytoplasm of the cells, and the protein level was lower in the lung cancer tissues compared with the normal tissues." (PMID 34769557, 2021). "Tissue microarrays of lung cancer patient cohorts demonstrated that a higher protein level of LPAR6 was correlated to better overall survival of LUAD rather than LUSC cohorts." (PMID 34769557, 2021). "All these discoveries indicated the crucial role of LPAR6 in lung cancer and also provided a potential correlation and identified the mechanism involved between LPAR6 and tumor–immune interactions." (PMID 34769557, 2021). "The lower promoter methylation levels of LPAR6 were detected in the earlier stage, implying that lower promoter methylation levels of LPAR6 were correlated with the earlier stages of the progress of lung cancer." (PMID 34769557, 2021). "Lung cancer patients with higher LPAR6 levels demonstrated better OS than those patients with relatively lower levels in LUAD patient cohorts, but not in LUSC patient cohorts." (PMID 34769557, 2021). "Moreover, we found that lower LPAR6 was negatively correlated with the clinical stage of lung cancer and the lymph node metastasis of patients." (PMID 34769557, 2021). "Moreover, LPAR6 significantly affects the prognostic potential of various cancers in The Cancer Genome Atlas Program (TCGA), especially in lung cancer." (PMID 34769557, 2021). "LinkedOmics were then used to analyze the genes that co-expressed with LPAR6 in lung cancers." (PMID 34769557, 2021). "Moreover, our data demonstrated that the immune-infiltration levels and diverse immune marker panels of the different subtypes of lung cancers (LUAD and LUSC) are associated with the expression level of LPAR6." (PMID 34769557, 2021). "Notably, the expression level of LPAR6 impacts OS in lung cancer significantly." (PMID 34769557, 2021). "Moreover, IHC staining for LPAR6 in two separate lung cancer cohorts with patients’ information was detected to analyze the correlation of the expression of LPAR6 and the clinicopathological parameters of lung cancer." (PMID 34769557, 2021). "In addition, the results of promoter methylation here could indicate how LPAR6 expression levels fluctuate in various stages of lung cancer." (PMID 34769557, 2021). "Next, we determined the expression levels of P2X sub-families P2RX1–7 and P2Y receptors P2RY1, P2RY2, P2RY4, P2RY5 (LPAR6), P2RY6, P2RY7 (LTB4R), P2RY8, P2RY9 (LPAR4), P2RY10–14 in normal lung tissues and lung cancer tissues." (PMID 32638267, 2020). "Our data show similar trends in murine models of KP lung cancer; however, we did not specifically analyze the role of LPAR6 in contributing to T cell migration." (PMID 37655662, 2023).
osteosarcoma (3 papers, 2021 to 2025). A usually aggressive malignant bone-forming mesenchymal neoplasm, predominantly affecting adolescents and young adults. "To further examine whether LPA synthesis mediated by osteosarcoma-derived AGPAT3 induces cytokine secretion through LPAR6, we treated THP-1-derived macrophages with XAA, an LPAR6 inhibitor, followed by co-culture experiments." (PMID 41502512, 2025). "Next, we investigated the correlation between LPAR6, ADGRE5, IL10, and IL6 in scRNA-seq and the TARGET osteosarcoma cohort." (PMID 41502512, 2025). "In TAMs, LPAR6 expression was positively correlated with ADGRE5, IL10, and IL6, which was further validated in the osteosarcoma cohort." (PMID 41502512, 2025). "The expression levels of LPAR1, LPAR6, S1PR1, and S1PR3 were relatively high in the osteosarcoma tumor tissues." (PMID 34302117, 2021). "Knockdown of AGPAT3 in osteosarcoma cells resulted in elevated lysophosphatidic acid (LPA) levels, which regulated the immune environment, inhibiting cytotoxic T cell function through TAMs’ LPAR6 signaling." (PMID 41502512, 2025). "Furthermore, AGPAT3 knockdown in osteosarcoma cell lines, combined with co-culture experiments, confirmed that LPA regulates TAM-mediated secretion of IL-10 and IL-6 via the LPAR6 signaling pathway." (PMID 41502512, 2025).
colorectal cancer (2 papers, 2021 to 2023). A primary or metastatic malignant neoplasm that affects the colon or rectum. "Among the mutated genes in the adenomatous tissue samples involved in our study, PCDHGB4, AHRR, KIF4, LPAR6, NBPF1, and NCEH1 were already associated with colorectal cancer formation, while ANKRD30A, ITIH1, and KIAA0556 were related to other types of cancers." (PMID 36765865, 2023). "However, the function of LPAR6 remains highly controversial since in colorectal cancer, scientists found that LPAR6 acts as a tumor suppressor, whereas it acts as a facilitator in the other types of tumors." (PMID 34769557, 2021).
COVID-19 (2 papers, 2021 to 2024). A disease caused by infection with severe acute respiratory syndrome coronavirus 2. "Furthermore, we modeled the LPAR1, LPAR3, and LPAR6 in a complex with the COVID-19 spike protein and performed a docking study of selected drugs with the LPAR-Spike complex." (PMID 38383841, 2024). "The proximity score of promethazine was significantly low partly by targeting genes including CALM1, KCNS1, LPAR4, LPAR6, P2RY12, P2PY8, and P2RX5, which were DEGs between T cell subsets of COVID-19 samples and healthy controls." (PMID 33919660, 2021).
Hypertension (2 papers, 2019 to 2024). The presence of chronic increased pressure in the systemic arterial system. "Although unsaturated LPAs evoke hypertension more efficiently than saturated LPAs, which is in agreement with our findings, this hypertensive response is mediated primarily by LPAR4 and LPAR6." (PMID 38999980, 2024).
ovarian carcinoma (2 papers, 2020 to 2021). A malignant neoplasm originating from the surface ovarian epithelium. "In line with this study, tumor associated T cells isolated from the ascites of ovarian cancer patients also showed higher expression of LPAR5 and LPAR6, whereas LPAR1-4 expression was comparable to ovarian cancer cells." (PMID 32397679, 2020). "Furthermore, the determination of patient cohorts from PrognoScan database and Kaplan–Meier Plotter demonstrated a high mRNA expression level of LPAR6 is correlated with better prognosis in breast, lung, bladder, colorectal, eye and ovarian cancer." (PMID 34769557, 2021).
acute lymphoblastic leukemia (1 paper, 2024). Leukemia with an acute onset, characterized by the presence of lymphoblasts in the bone marrow and the peripheral blood. "Familial 46, XY Disorder of Sexual Development (DSD) was discovered in a Ph+, BCR::ABL1P210+ Acute Lymphoblastic Leukemia (ALL) female with RCBTB2::LPAR6 fusion gene." (PMID 39091920, 2024).
atherosclerosis (1 paper, 2023). A disease characterized by the build-up of fatty material and calcium deposition in the arterial wall resulting in partial or complete occlusion of the arterial lumen. "LPAR6 can induce actin stress crack formation through the RhoA/ROCK pathway to increase endothelial permeability and advance the occurrence of atherosclerosis." (PMID 37342437, 2023).
Insulin resistance (1 paper, 2023). Increased resistance towards insulin, that is, diminished effectiveness of insulin in reducing blood glucose levels. "In addition, several energy metabolic processes, such as the PI3K-Akt pathway (EPHA2, FLT4, ITGA5, and LPAR6), cholesterol metabolism (APOE and CD36), and insulin resistance (FOLR1, CALM14, and PPP1R3A), were enriched in ApoE4 mice." (PMID 36720919, 2023).
lung adenocarcinoma (1 paper, 2021). A carcinoma that arises from the lung and is characterized by the presence of malignant glandular epithelial cells. "Immunohistochemistry (IHC) for LPAR6 in lung adenocarcinoma (LUAD) and lung squamous cell carcinoma (LUSC) tissue microarray with patients’ information was detected." (PMID 34769557, 2021).
skin cutaneous melanoma (1 paper, 2021). "Investigation of the TCGA database enclosed that the higher LPAR6 expression level is correlated with better prognostic potential in ACC, LGG, skin cutaneous melanoma (SKCM)." (PMID 34769557, 2021).
squamous cell carcinoma (1 paper, 2017). A carcinoma arising from squamous epithelial cells. "Overall, targeting LPAR6 will offer an opportunity for enhancing drug efficacy in cancer, especially in squamous cell carcinoma and metastatic prostate cancer." (PMID 29211777, 2017).
triple-negative breast carcinoma (1 paper, 2023). An invasive breast carcinoma which is negative for expression of estrogen receptor (ER), progesterone receptor (PR), and human epidermal growth factor receptor 2 (HER2). "LPAR1 and LPAR6 gene expression were highest in ER+HER2– (estrogen-receptor-positive, human-epidermal-growth-factor-receptor-negative) tumors and lowest in TNBC (triple negative breast cancer) tumors in all three cohorts, while this pattern was reversed for LPAR2 and LPAR3 (all p < 0.001)." (PMID 37372960, 2023).
tumor (27 papers, 2012 to 2025). "One of the richest sources of LPA is platelets, and activation of LPAR subtypes (LPAR1 to LPAR6) has been linked to tumor cell proliferation, migration, cytokine production, and angiogenesis." (PMID 36806315, 2023). "All these indicate that LPAR6 plays an important role in cancer, whereas the relationship between LPAR6 and tumor biology and the underlying mechanism involved is still unclear." (PMID 34769557, 2021). "The higher level of LPAR5 and LPAR6 in tumor tissue most likely reflects the presence of tumor‐associated immune cells, which is consistent with our own data." (PMID 30353652, 2019). "Low LPAR6 expression in the tumor was associated with poor prognosis." (PMID 31636669, 2019). "Hence, the interactions between LPAR6 and the immunocytes in the tumor microenvironment could be an underlying mechanism for the correlation of LPAR6 expression level with the immune infiltration level and a better prognosis in LUAD patients." (PMID 34769557, 2021). "Interestingly, immune infiltration analysis via the TIMER platform showed a significant negative correlation between LPAR6 expression and tumor purity, suggesting that high LPAR6 expression may be closely associated with infiltration of non-tumor components such as immune cells." (PMID 40362442, 2025). "Compared to the control group, tumor samples from the LPAR6 overexpression group showed reduced Ki-67 expression and increased LPAR6 expression." (PMID 40362442, 2025). "Through in vivo experiments, we observed that LPAR6 plays a positive role in inhibiting tumor initiation and progression, further supporting its potential as a therapeutic target." (PMID 40362442, 2025). "In vivo, LPAR6 overexpression in a nude mouse xenograft model significantly reduced tumor growth rate and volume, accompanied by decreased Ki-67 expression in tumor tissues, as shown by immunohistochemical analysis." (PMID 40362442, 2025). "Enhanced cell migration is a marker of tumor malignancy, and the results of our cell migration assay similarly showed that LPAR6 overexpression significantly reduced cell migration." (PMID 40362442, 2025). "The I subgroup exhibited significantly greater LPAR6 expression than the other subgroups (P = 0.002), which was previously associated with negative regulation of CD8 + T-cell tumor infiltration." (PMID 39300154, 2024). "On the other hand, melanoma tumour-derived LPA activates LPAR6 on the surface of cytotoxic CD8+ T-cells to suppress tumour infiltration, suggesting that LPA functions as a T-cell repellent." (PMID 38607068, 2024). "While almost all naive CD8+ T cells express LPAR2, LPAR5, and LPAR6, we next wanted to analyze the expression of these receptors on tumor-infiltrating CD8+ T cells." (PMID 37655662, 2023). "On CD8+ T cells, tumor-derived LPA binds to LPAR6 and prevents tumor infiltration by inhibiting migration." (PMID 37842241, 2023). "Our analysis suggested that both LPAR1 and LPAR6 expression were beneficial to NB patients’ survival, possibly involved in the regulation of tumor metastasis mediated by LPA." (PMID 35884407, 2022). "Consistent with the results of in vitro experiments and bioinformatics analyses, patients with high LPAR6 level were demonstrated to have a good prognosis, thereby providing further evidence for its role as a tumor suppressor." (PMID 34510318, 2022). "High LPAR6 expression relates to a high infiltration level of DCs in the tumor tissue of LUAD patients, DC markers such as HLA-DQB1, CD1C and NRP1 show significant correlations with LPAR6 expression both in the tumor tissue in LUAD." (PMID 34769557, 2021). "The results further confirm that LPAR6 is specifically correlated with immune infiltrating cells in LUAD which suggests that LPAR6 plays a vital role in immune cells recruiting the tumor tissue in LUAD patients." (PMID 34769557, 2021).
tumor (continued). "In summary, we demonstrated that the LPAR6 was downregulated in the tumor tissue of LUAD patients and its mRNA expression was positive associated with the OS of LUAD patients base on the databases and TMA cohorts." (PMID 34769557, 2021). "The correlation between LPAR6 mRNA expression and the marker gene panel of immune cells implicates the role of LPAR6 in regulating tumor immunology in these types of cancer." (PMID 34769557, 2021). "The more interesting thing is that the expression levels of most of the marker sets of these immunocytes have strong correlations with LPAR6 expression in the tumor tissue of LUAD patients." (PMID 34769557, 2021). "For example, the growth and progression of HCC are maintained along with the autocrine loop produced by LPAR6 in tumor cells 77,78." (PMID 32284748, 2020). "According to a study, LPAR1, 3 and 6 expression is increased in the livers of patients with HCC, and underlying cirrhosis or HCV infection, compared to healthy livers with LPAR6 expression being stronger in HCC tissue than in paired non-tumor liver tissue." (PMID 31652837, 2019). "RNAi-mediated genetic deletion of Lpar6 impaired HCC tumor growth in tumor xenograft assays, probably through a Signal-transducer-and-activator-of-transcription-3 (STAT3)/proto-oncogene pim-3-dependent mechanism." (PMID 31652837, 2019). "Recently, it has been reported that LPAR6 sustains proliferation capacity and tumour growth by transcriptional activation of a proto-oncogene Pim-3 in the liver cancer patients." (PMID 29211777, 2017). "The results showed that the average tumor volume in the LPAR6 overexpression group was significantly smaller in nude mice, and weekly tumor volume measurements indicated that LPAR6 overexpression significantly slowed tumor growth." (PMID 40362442, 2025). "The results show that the mRNA expression level of LPAR6 has significant negative correlations with tumor purity in 26 types of cancer which indicating LPAR6 somehow related to recruiting lymphocytes to tumor and significant correlated with B cell infiltration levels in 13 types of cancers." (PMID 34769557, 2021). "In-depth studies need to be done on whether LPAR6 is a crucial factor that mediating the de-polarization of macrophages and remodel tumor microenvironment." (PMID 34769557, 2021). "This exciting finding indicates that LPAR6 may regulate macrophage de-polarization in the tumor microenvironment of the LUAD and LPAR6 might be a novel target for LUAD therapy." (PMID 34769557, 2021). "In addition, we analyzed the correlation of LPAR6 with tumor-infiltrating immune cells (TIICs) in various tumor microenvironments via TIMER." (PMID 34769557, 2021). "LPAR6 and its modulation on tumor microenvironment may serve as a novel therapeutic target for LUAD." (PMID 34769557, 2021). "Moreover, the relationship of LPAR6 to the potential of prognosis and tumor infiltration immune cells in different types of cancer are still unclarified." (PMID 34769557, 2021). "Knockdown of LPAR6 in cell experiments enhanced tumor cell proliferation and invasion." (PMID 32284748, 2020). "While primary tumor cells express predominantly genes encoding EDG‐type receptors (LPA1‐3), immune cells (TAMs and TATs) also express genes for the non‐EDG receptors LPAR5 and LPAR6 at high levels." (PMID 30353652, 2019). "Furthermore, LPAR6 mediated HCC tumorigenicity in tumor xenografts, probably through a STAT3/pim-3-dependent mechanism." (PMID 31652837, 2019). "Further correlation analysis indicated that LPAR6 expression was positively associated with infiltration levels of various immune cells, particularly CD8+ T cells, implying that LPAR6 may be involved in regulating antitumor immune responses and shaping the tumor immune microenvironment." (PMID 40362442, 2025).